TSPO (translocator protein)
Diseases named in the same sentence as TSPO in open-access papers (continued):
Sharing a sentence is not in itself a finding about the gene and the disease.
Sepsis (11 papers, 2014 to 2025). Sepsis is defined as life-threatening organ dysfunction caused by a dysregulated host response to infection. "Even considering these limitations, low plasma TSPO concentration in sepsis suggested a possible diagnostic marker for sepsis." (PMID 39495982, 2024). "A study suggests that in sepsis-associated liver injury, TSPO may influence the pathological process by promoting inflammatory responses and exacerbating liver injury." (PMID 41424725, 2025). "Our findings indicate that TSPO expression is significantly upregulated in sepsis patients, supporting its potential role in promoting inflammatory and immune responses." (PMID 41424725, 2025). "Our study observes that plasma TSPO concentrations are significantly lower in patients with sepsis compared to healthy controls." (PMID 39495982, 2024). "In the present study, we have demonstrated that the plasma TSPO concentrations of patients with sepsis admitted to the ICU are significantly lower than those of healthy controls." (PMID 39495982, 2024). "The plasma TSPO concentrations of the patients with sepsis were significantly lower than those of healthy controls (0.094 vs 0.25 ng/mL, P < .001)." (PMID 39495982, 2024). "Due to its role in immune response, TSPO has been of great interest as a potential therapeutic target in inflammatory conditions such as sepsis." (PMID 38245687, 2024). "The plasma TSPO concentrations were below the detection sensitivity in 45 (87%) of the patients with sepsis and in 7 (25%) of the healthy controls." (PMID 39495982, 2024). "In this study, we compared the circulating TSPO concentrations of patients with sepsis and healthy controls to investigate the utility of plasma TSPO for the diagnosis of sepsis." (PMID 39495982, 2024). "We also investigated the relationships of TSPO concentration with the severity of sepsis, complications, and prognosis of the patients." (PMID 39495982, 2024). "Receiver operating characteristic analysis was used to evaluate the usefulness of plasma TSPO concentration for the diagnosis of sepsis." (PMID 39495982, 2024). "In future studies, it will be necessary to investigate how TSPO expression changes during the acute and chronic phases of sepsis progression across various tissues." (PMID 39495982, 2024). "In summary, the present study identified SIGLEC9, TSPO, CKS1B, and PTTG3P as the genetic biomarkers and established a four-gene-based model for the effective diagnosis and risk prediction of sepsis/se-ARDS based on gene co-expression network." (PMID 35844622, 2022). "Further correlation analysis based on SIGLEC9, TSPO, CKS1B, and PTTG3P was carried out to identify the potential interactions and effects of these diagnostic biomarkers during sepsis/se-ARDS development." (PMID 35844622, 2022). "The sepsis survivors and sham groups from 24-h to 10-day groups were subjected to the non-invasive TSPO–PET scan followed by CT imaging." (PMID 35606817, 2022). "TSPO PET imaging can potentially be used to quantify SIRS and sepsis-associated organ-level immunoreactivity and assess the effectiveness of therapeutic and preventative approaches for associated organ failures, in vivo." (PMID 36439175, 2022). "Our study demonstrated that the acute-phase response of sepsis increased TSPO uptake and glial cell activation, and by the end of 10 days after surgery, the antibiotic treatment and the host immune response cleared the active source of infection." (PMID 35606817, 2022). "Afterwards, a sepsis/se-ARDS risk nomogram model that involves SIGLEC9, TSPO, CKS1B, and PTTG3P as the independent predictors was constructed." (PMID 35844622, 2022). "Specifically, knockdown of TSPO in a mouse model of sepsis inhibited the polarization of hepatic macrophages towards a pro-inflammatory M1 phenotype and promoted their polarization towards an anti-inflammatory M2 phenotype, leading to a reduction in serum levels of pro-inflammatory cytokines." (PMID 41424725, 2025).
Sepsis (continued). "This suggests that TSPO may play a key role in regulating inflammatory responses and immune cell function in sepsis." (PMID 41424725, 2025). "During inflammation, TSPO expression is upregulated in activated immune cells, which contributes to the production of pro-inflammatory cytokines, ROS, and NO that play a significant role in the pathogenesis of sepsis." (PMID 38245687, 2024). "The plasma TSPO concentrations of the patients with sepsis were significantly lower than those of the healthy controls (0.094 vs 0.25 ng/mL, P < .001), and receiver operating characteristic analysis generated an area under the curve of 0.81 (95% confidence interval: 0.72–0.91)." (PMID 39495982, 2024). "The variability in sample collection timing, potential influence of medications, age differences between groups, and the small subset of measurable TSPO levels in sepsis patients could affect the results." (PMID 39495982, 2024). "Therefore, the aim of the present study was to compare the circulating TSPO concentrations of patients with sepsis with those of healthy controls, and to evaluate the potential clinical utility of TSPO for the diagnosis of sepsis." (PMID 39495982, 2024). "TSPO may be a marker of inflammatory responses in the brain and other organs, but there have been few studies of the potential clinical significance of measuring the circulating TSPO concentration, especially in patients with sepsis." (PMID 39495982, 2024). "Third, the age of the patients with sepsis and healthy controls in the present study differed greatly, and therefore age may have affected the TSPO concentrations of the patients." (PMID 39495982, 2024). "Furthermore, ROC analysis suggested the potential utility of TSPO as a useful marker for the diagnosis of sepsis." (PMID 39495982, 2024). "In sepsis, cognitive damage and microglial activation could be reduced by modulation of TSPO by antagonist PK-11195." (PMID 36820206, 2023). "Sepsis triggered the expression of TSPO, and the pro-apoptotic function of TSPO may involve the modulation of the channel formed by the mitochondrial voltage-dependent anion channel (VDAC) and the adenine nucleotide transporter (ANT)." (PMID 35606817, 2022). "Sepsis increased the expression of the TSPO in our research." (PMID 35606817, 2022). "Moreover, the levels of immune cell infiltration in the progress of sepsis/se-ARDS promoted their further correlation analysis based on SIGLEC9, TSPO, CKS1B, and PTTG3P, the diagnostic biomarkers identified in the study." (PMID 35844622, 2022). "However, despite these limitations, TSPO may be useful for the diagnosis of sepsis, and this possibility warrants further investigation." (PMID 39495982, 2024). "Plasma TSPO may be a useful biomarker for the diagnosis of sepsis." (PMID 39495982, 2024). "Finally, the TSPO concentration could only be measured in 7 patients with sepsis (13.4%), which may have been responsible for the weak associations between TSPO and clinical outcomes." (PMID 39495982, 2024). "Group B Strep sepsis was significantly associated with multiple cell clusters, including C8_DC, C9_STOM, C10_ULK1, C12_mix, C13_UBE2Z, and C16_B, and its signature genes, including CKAP4, CPEB4, TSPO, and TXN, were significantly upregulated in multiple relevant clusters." (PMID 37919720, 2023). "The expressions of four genes were remarkably related to each other, and it is apparent that the highly positive correlations between SIGLEC9 and TSPO and between CKS1B and PTTG3P were spectacularly remarkable at all the stages of sepsis/se-ARDS progression." (PMID 35844622, 2022). "During the development of sepsis/se-ARDS, the expressions of the identified biomarkers including SIGLEC9, TSPO, CKS1B and PTTG3P were all regulated remarkably and generally exhibited notable correlations with the stages of sepsis/se-ARDS." (PMID 35844622, 2022).
Sepsis (continued). "At 10 days after sepsis, the data shows significant increases in the IBA-1 (PFC and hippocampus, p < 0.05), GFAP (PFC, p < 0.05 and hippocampus, p ≥ 0.05), and TSPO (PFC and hippocampus, p < 0.001)." (PMID 35606817, 2022). "Both SIGLEC9 and TSPO were significantly upregulated on sepsis day 0 and then descended a bit more on sepsis day 7 (***P<0.001) during sepsis development, while both CKS1B and PTTG3P appeared to be steadily upregulated on sepsis day 0 and day 7 (*P<0.05)." (PMID 35844622, 2022). "SIGLEC9, TSPO, CKS1B, and PTTG3P all exhibited remarkable changes of upregulations in the sepsis group compared with control group in both datasets with P<0.05 (except for CKS1B in GSE28750), which proved the great diagnostic and predictive performance of these four biomarkers." (PMID 35844622, 2022). "Besides, SIGLEC9, TSPO, CKS1B and PTTG3P were considerably correlated with the infiltration of various immune cells including neutrophils and monocytes during sepsis/se-ARDS." (PMID 35844622, 2022). "Nevertheless, TSPO targeting in PET has been sparsely used to evaluate peripheral inflammation in preclinical and clinical models, with only a handful of published studies, none of which focus on sepsis-induced inflammation in peripheral organs, beyond the lungs." (PMID 36439175, 2022).
fibromyalgia (10 papers, 2011 to 2025). A chronic disorder of unknown etiology characterized by pain, stiffness, and tenderness in the muscles of neck, shoulders, back, hips, arms, and legs. "The translocator protein (TSPO) is associated with symptom severity and cerebral pain processing in patients with fibromyalgia." (PMID 29876878, 2019). "Mediation analysis indicated that fibromyalgianess modulated the relationship between TSPO expression and somatosensory cortex–thalamus connectivity, underscoring the role of neuroinflammation in the centralization of pain." (PMID 40565912, 2025). "The neuroinflammatory changes were positively correlated with pain intensity and fatigue levels in fibromyalgia, positioning TSPO-PET as a candidate biomarker." (PMID 41225995, 2025). "Imaging studies using the radioligand 11C-PBR28, showed an increase in brain levels of the translocator protein (TSPO), a marker of glial activation, in people with low back pain and fibromyalgia." (PMID 36387416, 2022). "This protein is upregulated during glial activation, and compared to mixed/low TSPO affinity binders, high TSPO affinity binders rated more severe pain and fibromyalgia symptoms." (PMID 29876878, 2019). "Furthermore, recent studies utilizing PET-computed tomography brain imaging with the 18 kDa Translocator Protein (TSPO) binding have revealed a widespread cortical glial activation in fibromyalgia patients." (PMID 41225995, 2025). "Moreover, TSPO expression has been found changed in several diseases and pathological conditions, including psychiatric diseases and fibromyalgia where altered densities of both SERT and TSPO have been reported." (PMID 21299850, 2011). "In this context, PET imaging may help define biologically distinct subgroups of fibromyalgia patients based on patterns of neuroinflammation (e.g., TSPO expression), neurotransmitter dysregulation (e.g., serotonergic or dopaminergic transporter availability), or regional metabolic alterations." (PMID 40565912, 2025). "A cerebral upregulation of the translocator protein (TSPO), a biomarker of glial activation, has been reported in fibromyalgia subjects (FMS)." (PMID 34142769, 2022). "Positron emission tomography (PET) imaging using ligands that bind to translocator protein (TSPO), a marker of microglial activation, has shown increased uptake in patients with chronic pain and fatigue, including those with fibromyalgia and systemic autoimmune diseases." (PMID 40649815, 2025). "Interestingly, platelet TSPO and SERT densities have been found altered in fibromyalgia, panic disorders and suicide attempters." (PMID 21299850, 2011).
hepatocellular carcinoma (10 papers, 2018 to 2025). A malignant tumor that arises from hepatocytes. "A recent study has reported that mitochondrial TSPO is highly expressed and inhibits ferroptosis in hepatocellular carcinoma cells by enhancing the Nrf2-dependent antioxidant defense system." (PMID 40842566, 2025). "They indicated that by inhibiting ferroptosis and immune evasion, mitochondrial TSPO promotes the progression of hepatocellular carcinoma." (PMID 39315094, 2024). "TSPO-silenced mitochondria from hepatocellular carcinoma cells were also found to have smaller mitochondria with fewer cristae." (PMID 39684592, 2024). "TSPO knockdown has been shown to disrupt mitochondrial function in hepatocellular carcinoma (HCC) by increasing ROS production and lowering mitochondrial membrane potential (ΔΨm), which in turn inhibited HCC cell proliferation." (PMID 39280415, 2024). "Mitochondrial translocator protein (TSPO) is highly expressed in hepatocellular carcinoma (HCC) and promotes HCC progression and metastasis." (PMID 36994647, 2023). "Another study indicated that TSPO is a poor biomarker for the diagnosis and prognosis of liver cancer, despite its upregulation in hepatocellular carcinomas." (PMID 30044440, 2018). "Furthermore, TSPO has been shown to regulate ferroptosis in hepatocellular carcinoma cells via P62-NRF2 pathway." (PMID 40842566, 2025).
retinal degeneration (10 papers, 2014 to 2025). Degeneration of the retina. "In the present study, we now show that selective up-regulation of TSPO is closely associated with the reactivity of microglia during retinal degeneration." (PMID 24397957, 2014). "Moreover, minocycline-mediated attenuation of retinal degeneration was associated with reduction in microglial reactivity and the expression of TSPO." (PMID 27315802, 2016). "Microglia activation is a hallmark of retinal degenerative diseases and we have previously demonstrated that pharmacological or genetic modulation of microglia-related genes including TSPO and galectin-3 can delay retinal degeneration." (PMID 38288111, 2023). "In this study, we showed that TSPO expression is directly connected to retinal microgliosis in a mouse model of retinal degeneration and in human retinal sections." (PMID 24397957, 2014). "Translocator protein (18 kDa) is highly expressed in reactive retinal microglia, and a recent study has shown that it can be successfully targeted to counteract microglial activation and bright light-induced mouse retinal degeneration." (PMID 26920853, 2016). "It is also interesting that in a TSPO deficient mouse model, the ability to mount a local microglial response to nerve cell injury was not compromised, and in a more recent TSPO knockout model, TSPO deficiency did not affect microglial number or morphology in models of retinal degeneration." (PMID 32102369, 2020). "This review article therefore focusses on translocator protein 18 kDa (TSPO) ligands and IFN-β as recent examples that have shown potent immunomodulatory effects in mouse models of light-induced retinal degeneration and laser-induced choroidal neovascularization (CNV)." (PMID 29977192, 2018).
astrocytoma (9 papers, 2009 to 2024). "High TSPO expression in astrocytoma has been shown to correlate with shorter survival and higher proliferation." (PMID 31963507, 2020). "Together these results suggest that NIR-conPK binds to a protein that is related to TSPO, and expressed by astrocytomas and microglia." (PMID 20020060, 2009). "Using qPCR, we found that DBT cells, a highly malignant mouse astrocytoma cell line, express high levels of TSPO mRNA compared to two other mouse astrocytoma cell lines, D30 and D1A cells." (PMID 20020060, 2009). "We describe a novel mechanism of TSPO silencing in IDH-mutant astrocytomas." (PMID 37697350, 2023). "For example, [11C]-PK 11195 reliably monitors increases in TSPO expression in brain tumors (including malignant astrocytomas), as well as in the activated microglia found in patients with multiple sclerosis, stroke, epilepsy, Alzheimer's disease, Huntington's disease and AIDS." (PMID 20020060, 2009). "On the contrary, there was no significant TSPO-PET signal elevation in any region of the contralateral hemispheres of patients with IDHmut astrocytoma WHO 2 (all P > 0.5)." (PMID 39150564, 2024). "In astrocytoma, TSPO is expressed in Iba1+ cells, but not GFAP+ astrocytes, while reactive astrocytes can contribute to the signal, in addition to reactive microglia." (PMID 31963507, 2020). "Conversely, we found that NIR-conPK did not compete for [3H]-PK 11195 binding in astrocytoma cell homogenate, but exhibited specific binding in intact astrocytoma cells in culture with nanomolar affinity, suggesting that NIR-conPK binds to a protein distinct, but related to, TSPO." (PMID 20020060, 2009). "Also, there is no precise information on TSPO in newly formed vessels in high-grade astrocytomas and oligodendrogliomas and on whether the altered conformation of normal vessels that are distorted by tumour growth might affect the modelling." (PMID 27077069, 2016). "Accordingly, treating intact astrocytoma cells and microglia in culture with cytokines led to significant changes in the amount of NIR-conPK specific binding without corresponding change in TSPO expression." (PMID 20020060, 2009).
Brain atrophy (9 papers, 2015 to 2025). Partial or complete wasting (loss) of brain tissue that was once present. "In rTg4510 mice, studies using PET imaging and immunohistochemistry confirmed that age-dependent TSPO accumulation followed pathological tau accumulation and brain atrophy." (PMID 33644757, 2021). "These TauTg mice exhibit aggressive neuropathology in cortical and hippocampal regions, developing TSPO-positive gliosis, which can be detected by PET and is closely associated with the progression of tau deposition and brain atrophy." (PMID 33740987, 2021). "PET imaging with translocator protein (TSPO) ligands to visualize microglial activity following TBI in vivo showed that areas with high microglial activation exhibited high levels of brain atrophy even many years after injury." (PMID 32545705, 2020). "Of particular interest, a recent study utilizing PET imaging found that retired NFL players with a history of mTBI had increased binding of [11C]DPA-713 to translocator protein, an indicator of neuroinflammation, as well as concomitant brain atrophy." (PMID 26683475, 2015). "There were no significant group differences between the groups in MRI measures of brain atrophy or PET uptake values for tracers targeted toward TSPO (marker of neuroinflammation), SV2A (marker of synaptic density), and fluorodeoxyglucose (marker of glucose metabolism) in 15-month-old female rats." (PMID 40359012, 2025). "Our findings of the age-dependent TSPO accumulation along with pathological tau accumulation and brain atrophy suggested that DAM phenotype might be involved in tau-induced neurodegeneration." (PMID 33644757, 2021). "Brain atrophy, tau accumulation, and neuroinflammation were assessed longitudinally using volumetric magnetic resonance imaging, tau-PET, and TSPO-PET, respectively." (PMID 33740987, 2021). "It should be noted that microglial activation in rTg4510 brains examined using translocator protein (TSPO) (18-kDa TSPO)-PET imaging showed significant correlation with both [11C]PBB3 level and brain atrophy (see text footnote 1)." (PMID 29375461, 2017).